CXCL13 (C-X-C motif chemokine ligand 13)
Diseases named in the same sentence as CXCL13 in open-access papers (continued):
Sharing a sentence is not in itself a finding about the gene and the disease.
MALT lymphoma (5 papers, 2015 to 2025). An indolent, extranodal type of non-Hodgkin lymphoma composed of small B-lymphocytes (centrocyte-like cells). "The pronounced upregulation of CXCL13 as well as the presence of a clear proliferation of B-cells in germinal centers in the present study seem to be in line with the higher risk to develop gastric MALT lymphoma in humans infected with NHPH compared to H. pylori infected patients." (PMID 25889172, 2015). "Immunofluorescence double staining showed the co-expression of CXCL13 and CXCR5 in MALT lymphoma samples." (PMID 40078987, 2025). "Consequently, targeting the CXCL13/CXCR5 signaling axis represents a promising immunotherapeutic approach for managing and treating ocular adnexal MALT lymphoma." (PMID 40078987, 2025). "In addition, several molecules such as CXCL13, CCL18, CCL19, CCL 20 and TLR 10 were found to be dysregulated in MALT lymphoma, suggesting that not only modulate H. pylori infection but also affect the risk of MALT lymphoma." (PMID 35008340, 2021).
nasopharyngeal carcinoma (5 papers, 2022 to 2025). A carcinoma arising from the nasopharyngeal epithelium. "A novel subpopulation of tumor-derived PD-1 + CXCR5_ CD4 + Th-CXCL13 cells has been discovered through research and plays a significant role in driving B cells into TLSs in nasopharyngeal carcinoma." (PMID 38216927, 2024). "However, in EBV‐associated nasopharyngeal carcinoma (NPC), the presence of PD‐1+ CXCR5− CD4+ Th‐CXCL13 cells within TLS may be associated with improved prognosis." (PMID 40591148, 2025).
sarcoidosis (5 papers, 2020 to 2023). Sarcoidosis is a multisystemic disorder of unknown cause characterized by the formation of immune granulomas in involved organs. "Expression of CXCL13, a chemokine and B-lymphocyte chemoattractant associated to calcium influx was downregulated in both sarcoidosis (lymph node) and TB granulomas but upregulated CM granulomas." (PMID 33276795, 2020). "The levels of CXCL13 were elevated 1423.6-fold in VKH disease, 298.3-fold in Behçet's disease, 107.1-fold in HLA-B27-associated uveitis and 458.2-fold in sarcoidosis compared to controls." (PMID 34869409, 2021). "Only three DEGs, SLAMF7, DC27, and CXCL13, were dysregulated in all three diseases (sarcoidosis, TB, CM)." (PMID 33276795, 2020). "Sarcoidosis was high in one of four cases, but there were few reports of a relationship between sarcoidosis and CXCL13." (PMID 32314548, 2020). "Hypercalcemia associated to granulomatous diseases is commonly reported, the potential pathogenic role of CXCL13 and CXCL14, both DEG in sarcoidosis and TB needs further investigation." (PMID 33276795, 2020). "Likewise, we also verified the over-expression of several other inflammation-associated genes including CCL19, CXCL13, and CYP27B1 in the lung of both TB and sarcoidosis patients." (PMID 33097805, 2020). "However, four cases of other diseases had high CSF CXCL13 over 1000 pg/mL, IgG4‐related disease: 1568 and 1043 pg/mL, sarcoidosis: 1390 pg/mL, and metastatic brain tumor: 1320 pg/mL." (PMID 32314548, 2020). "However, CXCL13 was elevated in the aqueous humor of uveitis including sarcoidosis." (PMID 32314548, 2020). "Among 20 similar signature genes shared by TB and sarcoidosis identified through RNA-Seq analysis, we further confirmed similar over-expression of MMP12, ADAMDEC1, CCL19, CXCL13, and CYP27B1 in TB and sarcoidosis lungs." (PMID 33097805, 2020).
synovitis (5 papers, 2012 to 2025). Inflammation of a synovial membrane. "The specific association with US parametres might explain why CXCL13 assessment at baseline was still associated with synovitis evolution at 12 months in our cohort." (PMID 22336440, 2012). "Thus, measurement of CXCL13 levels may provide an advantage in the objective assessment of the degree of synovitis compared to routine markers that only indirectly are linked to joint inflammation." (PMID 22336440, 2012). "CXCL13 is involved in recruiting CXCR5+ B cells to synovium in RA and was associated with disease activity, ultrasonographic synovitis and long-term radiographic progression." (PMID 39925810, 2025). "In this study we found that CXCL13 levels correlated with swollen joint counts and ultrasound findings of synovitis." (PMID 33292827, 2020). "Four studies examined CXCL13 as a marker of ultrasound synovitis, reporting a correlation with ultrasonographic scores for Grey Scale (r = 0.27) and Power Doppler signals (r = 0.26–0.69)." (PMID 33292827, 2020). "CXCL13 emerges as a new biological marker in early RA, accurate in assessing the severity of synovitis and the persistence of US-PD activity over time in response to conventional treatments." (PMID 22336440, 2012). "In particular, CXCL13 appeared as a marker of synovitis, as assessed clinically and, more relevantly, by US." (PMID 22336440, 2012). "In 2 studies, CXCL13 levels correlated with ultrasonographic evidence of synovitis." (PMID 33292827, 2020). "In addition to its specific relationship with clinical and US synovitis, CXCL13 showed further correlation with the autoantibody status." (PMID 22336440, 2012). "Definite confirmation of the specific relationship between serum CXCL13 and PD synovitis would require paired longitudinal assessments at each time point during follow-up, a possibility that was limited in our study due to the unavailability of serum samples matched with US at follow-up." (PMID 22336440, 2012). "The predictive value of CXCL13 appears of utmost clinical importance when considering patients in LDA states, in which different thresholds of residual imaging synovitis might be of importance for subsequent clinical and radiological evolution." (PMID 22336440, 2012).
uveitis (5 papers, 2019 to 2022). An inflammatory process affecting a part of or the entire uvea. "The levels of the B cell chemoattractant CXCL13 in aqueous humor samples from patients with uveitis associated with VKH disease largely exceeded those in patients with Behçet's disease or HLA-B27-associated uveitis." (PMID 34869409, 2021). "CXCL13 levels in VKH disease were significantly higher than the levels in Behçet's disease and HLA-B27-associated uveitis." (PMID 34869409, 2021). "Secondly, adjunctive analysis of the CXCL13, CXCL10 and CXCL8 levels in the AH of patients with uveitis can be of value in the diagnosis and treatment of uveitis, either as part of a routine workup and assessment of the response to treatment or to confirm or refute a diagnosis of ocular syphilis." (PMID 38983560, 2022). "The group of patients with optic neuropathy had the lowest level of AH CXCL13, which confirms the clinical diagnosis of an optic neuritis without intraocular inflammation (uveitis)." (PMID 38983560, 2022).
vasculitis (5 papers, 2019 to 2024). "Although the underlying mechanisms remain unclear, previous studies reported that glucocorticoids increased serum MMP-3 levels and also that glucocorticoids were associated with elevated CXCL13 levels in multiple diseases, including vasculitis." (PMID 33743769, 2021). "Another clinically relevant marker is CXCL-13, which shows potential for distinguishing between active vasculitis and long-term remission." (PMID 39702436, 2024). "Receiver operating characteristic curve analysis (ROC) revealed a good ability of MMP-3, CXCL-13 and C5a in distinguishing active vasculitis (Active Group) from the Control Group (AUC > 0.8)." (PMID 33664330, 2021). "Receiver operating characteristic curve analysis (ROC) was used to evaluate MMP-3, CXCL-13 and C5a as markers of the different phases of vasculitis." (PMID 33664330, 2021). "CXCL-13 seems to be a potential marker for distinguishing active vasculitis from long term remission." (PMID 33664330, 2021). "CXCL-13 levels were also significantly higher in all groups of patients who suffered from vasculitis in comparison to the Control Group." (PMID 33664330, 2021). "CXCL-13 seems to be a potential marker in distinguishing active vasculitis from long term remission." (PMID 33664330, 2021). "Whereas only CXCL-13 had the potential ability to distinguish active vasculitis (Active Group) from long term remission (Long R Group, AUC > 0.8)." (PMID 33664330, 2021). "In summary, MMP-3, CXCL-13, C5a can be helpful in differentiating an active phase of vasculitis from other pathologies." (PMID 33664330, 2021). "MMP-3, CXCL-13, C5a can be potential markers in differentiating an active phase of vasculitis from other pathologies." (PMID 33664330, 2021). "Therefore, CXCL-13 is examined as a potential vasculitis biomarker." (PMID 33664330, 2021).
anemia (4 papers, 2022 to 2025). A reduction in the number of red blood cells, the amount of hemoglobin, and/or the volume of packed red blood cells. "Only CXCL-13 and CCL-24 in both peripheral (p = 0.01 and <0.0001, respectively) and placental (p = 0.01 and p = 0.02, respectively) plasma were associated significantly with maternal anemia in PM+ women when compared to the healthy controls." (PMID 36689438, 2023). "Interestingly, the increase in CXCL-13 was accompanied by decrease in CCL-24, suggesting opposing roles for these two chemokines in PM-associated anemia." (PMID 36689438, 2023). "We next assessed whether inflammation marker C-reactive protein (CRP) and neutrophils counts, and anemia marker hemoglobin content (Hb) were correlated with serum CXCL13 levels in the IBD patients." (PMID 36172372, 2022). "Additionally, the correlation of serum CXCL13 levels with disease severity biomarkers complement C3, renal function related biomarkers Cr and BUN, nutritional biomarker serum Alb, and anemia biomarker Hb was analyzed in patients with LN." (PMID 41164191, 2025). "Speaking of the association with anemia or thrombocytopenia and CD38 expressions, CLL patients with anemia and/or thrombocytopenia had significantly higher plasma levels of CXCL13 and galectin-9 than patients without these complications (p < 0.05, p < 0.0001, and p < 0.0001, respectively)." (PMID 37946029, 2024).
autoimmune encephalitis (4 papers, 2016 to 2024). Inflammation of the brain secondary to an immune response triggered by the body itself. "The data on CSF cytokine and chemokine profile in autoimmune encephalitis is limited in the literature, and have shown elevation of CSF IL-6 and CXCL13 in previous studies." (PMID 27575749, 2016). "The subgroup analysis in autoimmune encephalitis group demonstrated no significant alteration of the CXCL13 concentration with high between-study heterogeneity (SMD, 1.39; 95% CI, -0.66–3.44; P = 0.18; Q = 12.23; P < 0.01; I2 = 92%)." (PMID 36048783, 2022).
chronic thromboembolic pulmonary hypertension (4 papers, 2016 to 2021). Chronic thromboembolic pulmonary hypertension (CTEPH) is characterized by the persistence of thromboemboli in the form of organized tissue obstructing the pulmonary arteries. "Although there are weak associations between serum CXCL13 and disease severity, CXCL13 is overexpressed in both idiopathic pulmonary artery hypertension and chronic thromboembolic pulmonary hypertension." (PMID 34374413, 2021). "We wondered whether CXCL13 may also play a role in chronic thromboembolic pulmonary hypertension (CTEPH) and whether serum levels of CXCL13 might serve as biomarkers in these conditions." (PMID 26927848, 2016).
co-infection (4 papers, 2016 to 2021). "Interestingly, plasma levels of CXCL13 were also associated with CMV co-infection which was reported to be a contributor to HIV-associated systemic inflammation." (PMID 30846990, 2019). "After co-infection (Ctrl + PRRSV-2/H3N2), TNF, IFN-γ, IL-12p40, IL-4 and CXCL-13 transcripts were all up-regulated (mean fold change of 2.43, 1.86, 3.47, 2.49 and 2.83, respectively)." (PMID 34858411, 2021). "Perhaps co-infection of T. pallidum and HIV promote the production of more CSF CXCL13 than T. pallidum infection alone." (PMID 27376011, 2016). "We observed PLWH with CMV co-infection to have higher plasma levels of CXCL13 than PLWH without CMV co-infection (p = 0.005)." (PMID 30846990, 2019).
epilepsy (4 papers, 2018 to 2024). A brain disorder characterized by episodes of abnormally increased neuronal discharge resulting in transient episodes of sensory or motor neurological dysfunction, or psychic dysfunction. "Levels were moderately elevated, but two patients (one with epilepsy and one with neurofibromatosis type 1) had highly elevated CXCL13 (4270 and 5746 pg/mL respectively)." (PMID 30083887, 2018). "Both CXCL13 and CXCR5 were upregulated in the brain in both patients with intractable epilepsy and a rat model of epilepsy with neuroinflammation." (PMID 33161894, 2020). "The chemokine CXCL13 and its receptor CXCR5 were upregulated in epilepsy patients' brain tissue." (PMID 38361811, 2024).
follicular dendritic cell sarcoma (4 papers, 2015 to 2022). A neoplasm composed of spindle to ovoid cells which have morphologic and immunophenotypic characteristics of follicular dendritic cells. "Finally, one intriguing possibility is a follicular dendritic cell sarcoma, which can arise from ubiquitous perivascular cells, and in humans can show aberrant NF-κB regulation and high expression of CXCL13, an alternative NF-κB driven gene." (PMID 34292968, 2021). "It is worth mentioning that follicular dendritic cell sarcoma (FDCS), a disease characterized by the malignant proliferation of FDCs itself, exhibits overexpressed FDCSP and overexpressed CXCL13, which cooperate with other genes to diagnose FDCS." (PMID 36291667, 2022). "Follicular dendritic cell sarcoma (FDCS) is specifically immunopositive to CD21, CD35, and/or CD23, vimentin, fascin, HLA-DR, EMA, D2-40, clusterin, and CXCL13." (PMID 25889780, 2015). "The pathogenesis of follicular dendritic cell sarcoma is largely unknown, however, knock out of B-cell TNF in mice has been related to follicular dendritic cell dysregulation through its impact on NF-κB pathways and CXCL13 chemokines." (PMID 37168632, 2022).
Granuloma (4 papers, 2020 to 2025). A compact, organized collection of mature mononuclear phagocytes, which may be but is not necessarily accompanied by accessory features such as necrosis. "Labeling of mRNA for the B cell selective chemokine CXCL13, also known as B-lymphocyte attractant, was markedly present at the periphery of granuloma associated follicle-like structures." (PMID 40468399, 2025).
head and neck squamous cell carcinoma (4 papers, 2021 to 2025). A squamous cell carcinoma that arises from any of the following anatomic sites: lip and oral cavity, nasal cavity, paranasal sinuses, pharynx, larynx, and salivary glands. "Furthermore, survival analysis using in 517 cases of head and neck squamous cell carcinomas showed that patients with higher CXCL13 expressions were associated with better overall survival (p = 0.0032)." (PMID 40352278, 2025). "CXCL13 could be used to determine the origin of squamous cell lung cancer in patients with head and neck squamous cell carcinoma (HNSCC), where a risk for lung metastasis exists." (PMID 34947813, 2021).
hepatitis B (4 papers, 2018 to 2025). "Studies have shown that prevaccination levels of CXCL11 and CXCL12 in healthy individuals and CXCL13 in HIV+ subjects may predict hepatitis B-vaccine response." (PMID 33431890, 2021). "We have recently reported a negative correlation between baseline levels of circulating CXCL-13 and hepatitis B vaccine responses in treated HIV infected adults." (PMID 30420858, 2018).
HIV-1 infection (4 papers, 2009 to 2021). The type species of lentivirus and the etiologic agent of acquired immunodeficiency syndrome (AIDS). "Plasma CXCL13 levels were associated with bnAbs at 6 months from HIV-1 infection but the correlation was lost after an additional 6 months." (PMID 33732259, 2021). "In addition to potential significance as a biomarker of GC function, increased plasma CXCL13 levels could have pathogenic significance during HIV-1 infection in view of their association with disease progression." (PMID 33732259, 2021). "The use of plasma CXCL13 as an adjunct to viral load for predicting the emergence of cross-neutralizing antibodies and bnAb during acute HIV-1 infection (and vaccines) should be investigated in a large cohort of HIV-1-infected patients." (PMID 33732259, 2021). "Thus, acute HIV-1 infection is associated with rapid and gradual increase in plasma levels of B cell-associated cytokines BAFF and CXCL13, respectively." (PMID 28943879, 2017). "We measured the dynamics of B cell subsets, plasma levels of BAFF and CXCL13 before infection and longitudinally during hyperacute HIV-1 infection and determined their influence on the emergence of cross-neutralizing antibodies at approximately 1 year postinfection (PI)." (PMID 28943879, 2017). "We have recently shown that during chronic HIV-1 infection, CD27+ and CD27− B-cells show an altered migration patterns due to alterations in expression of the receptor-ligand pair CXCR5/CXCL13." (PMID 19412542, 2009).
inflammatory bowel disease (4 papers, 2022 to 2026). A spectrum of small and large bowel inflammatory diseases of unknown etiology. "In this study, we investigate the role of CXCL13 in the pathogenesis of inflammatory bowel disease using both clinical specimens and animal models." (PMID 36172372, 2022). "Furthermore, CXCL13 is involved in the pathogenesis of inflammatory bowel disease, and the concentration of CXCL13 is positively correlated with the severity of the inflammatory response." (PMID 36172372, 2022).
interstitial lung disease (4 papers, 2016 to 2022). A diverse group of lung diseases that affect the lung parenchyma. "The increased levels of CXCL13 are associated with severe prognosis and increased mortality in all interstitial lung diseases." (PMID 36560669, 2022). "The increased levels of CXCL13 are associated with severe prognosis and increased mortality in all the interstitial lung diseases." (PMID 34373466, 2021). "Based on our results, CXCL13 is associated with the pathogenesis of pSS, such as immunoglobulin production, and is linked to the activity of lymphadenopathy, glandular manifestation, interstitial lung disease (ILD) and biological status of the salivary glands." (PMID 27180164, 2016).
ischemic stroke (4 papers, 2022 to 2024). A stroke disorder caused by obstruction of blood flow to the brain, due to thrombotic (local blood clot formation) or embolic (due to a blood clot or other material traveling from another site) event. "It has also been found that upregulation of CXCL13 levels in mice with ischemic stroke selectively recruits B cells and attenuates brain injury." (PMID 39206161, 2024). "The CSF of 212 patients with ischemic stroke was analysed for intrathecal Ig synthesis by determining the CSF specific IgG index / OCBs and CXCL13 concentrations as markers of CNS specific B cell activation." (PMID 37000850, 2023). "After a unilateral ischemic stroke in mice, CXCL13, a B cell-recruiting chemokine, is upregulated in cortical vessels of the ischemic hemisphere within 24 h." (PMID 36446955, 2022). "Cells expressing CXCR5, the receptor for the CXCL13 ligand, have been found in both hemispheres of the brain acutely after unilateral ischemic stroke, suggesting that CXCL13 expression is more widespread rather than localized to the area of infarct." (PMID 36446955, 2022). "Therefore, this study uncovers an important role of CXCL13 expressed on inflamed cerebral vessels in recruiting IL-21-producing TFH cells via CXCR5 to produce neuroinflammation and subsequent neuronal death in ischemic stroke." (PMID 39472796, 2024).